CHRDL1 (chordin like 1)
Diseases named in the same sentence as CHRDL1 in open-access papers (continued):
Sharing a sentence is not in itself a finding about the gene and the disease.
oral cancer (1 paper, 2024). "In this study, we analyzed the differential genes of CHRDL1 in oral cancer through NCBI sequencing data analysis, which was further validated by RT-qPCR." (PMID 39462350, 2024). "To explore the target genes regulated by CHRDL1, we conducted an analysis using sequencing results of differentially expressed genes in oral cancer cells overexpressing CHRDL1 obtained from the NCBI database." (PMID 39462350, 2024). "Furthermore, studies have reported that when the CHRDL1 gene is silenced, oral cancer cells also exhibit activation of EMT-like characteristics." (PMID 39462350, 2024). "This study primarily explores the effects of CHRDL1 and MED29 on oral cancer metastasis and invasion, thus employing a tail vein injection nude mouse metastasis model." (PMID 39462350, 2024). "In the co-transfected group, migration was between the CHRDL1 overexpression group and the MED29 group, suggesting that MED29 can reverse the inhibitory effect of CHRDL1 on oral cancer migration, indicating that CHRDL1 plays a regulatory role in the CHRDL1-MED29 signaling axis." (PMID 39462350, 2024).
prostate adenocarcinoma (1 paper, 2025). "Specifically, expression of CHRDL1 was a risk factor for 7 types of cancers, including KIPAN, STAD, KIRC, COAD, COADREAD, and BLCA (HR > 1, p < 0.05), and it was a protective factor for 5 types of cancers, such as prostate adenocarcinoma (PRAD), SKCM-M, SKCM, MESO, and LUAD (HR < 1, p < 0.05)." (PMID 40230414, 2025).
T-cell acute lymphoblastic leukemia (1 paper, 2022). Acute lymphoblastic leukemia of T-cell origin. "Abnormally elevated CHRDL1 was also found in T cell acute lymphoblastic leukemia." (PMID 35021154, 2022).
T-cell leukemia (1 paper, 2022). A malignant disease of the T-lymphocytes in the bone marrow, thymus, and/or blood. "In T-cell leukemia, the ectopic activity of CHRDL1 has been shown to inhibit BMP-signaling, which results in the aberrant expression of NKL homeobox gene MSX1." (PMID 35328612, 2022).
testicular germ cell tumor (1 paper, 2025). A germ cell tumor arising from the testis. "In UCEC, PRAD, KICH and testicular germ cell tumor (TGCT), CHRDL1 was significantly negatively correlated with class." (PMID 40230414, 2025).
tumor (26 papers, 2009 to 2025). "For instance, we identified CHRDL1, the downregulation of which was associated with poor survival and mechanistically with cancer progression and metastasis, indicating the tumor-suppressing role of CHRDL1." (PMID 34439480, 2021). "Malignant-like features, such as irregular shape, uncircumscribed margin, no posterior acoustic enhancement, and calcifications, were correlated with CHRDL1 expression and low risk of tumor recurrence (P<0.05)." (PMID 33542899, 2020). "Additionally, Chrdl1 has been associated with the suppression of tumor growth and metastasis." (PMID 39152126, 2024). "Mechanistically, CHRDL1 exerts its tumor-suppressive effects by antagonizing the BMP4/SMAD signaling pathway." (PMID 40837015, 2025). "Increased CHRDL1 expression in CRC cell lines has a tumour‐suppressive effect, which was emulated in xenograft models." (PMID 40212011, 2025). "CHRDL1 expression levels showed significant variation across different cancer types, with tumor tissues typically demonstrating lower expression compared to their normal counterparts." (PMID 40230414, 2025). "Small animal imaging was performed 14 days post-tumor inoculation, revealing significantly higher fluorescence intensity in the shCHRDL1 group, indicating that downregulation of CHRDL1 promotes tumor growth." (PMID 40230414, 2025). "We observed that CHRDL1 functions as a tumor suppressor in LUAD by inhibiting cell growth and proliferation." (PMID 40230414, 2025). "Wound healing assays confirmed that CHRDL1 overexpression inhibits tumor cell migration, and knockdown increases it." (PMID 40230414, 2025). "CHRDL1 is positively correlated with the tumor immune cycle, while negatively correlated with base excision repair, cell cycle, and DNA replication." (PMID 40230414, 2025). "To further investigate the effects of CHRDL1 on the growth and proliferation of LUAD cells in vivo, we subcutaneously injected LUAD cells with either high or low (PC9) expression levels of CHRDL1 into nude mice and monitored the tumor formation." (PMID 40230414, 2025). "Studies have confirmed that CHRDL1, as a tumor suppressor gene, inhibits the occurrence and metastasis of gastric cancer." (PMID 39462350, 2024). "To verify the tumor-suppressive functions of the candidate hub genes, we selected CHRDL1 and FAM107A genes which showed the strongest downregulation in the LUSC samples." (PMID 38188687, 2023). "Our study identified commonly downregulated genes in two cohorts of LUSC datasets, and verified the tumor-suppressive functions of two hub genes in the PPI network (CHRDL1 and FAM107A)." (PMID 38188687, 2023). "As a tumor suppressor, CHRDL1 is down-expressed in various cancer tissues, and a high CHRDL1 expression level induced decreased tumor progression." (PMID 35186082, 2022). "Subsequently, we applied RT-PCR to detect the expression level of GAPDH, GNPNAT1, HTATIP2, MFI2, PKP2, RGS20, and CHRDL1 in these 10 tumor tissues." (PMID 35186082, 2022). "Obviously, CHRDL1 expression of tumor tissues was significantly decreased compared with normal samples in LUAD (P<0.001)." (PMID 35021154, 2022).
tumor (continued). "This leaves the open questions on where CHRDL1 originates in a multicellular tumour and how it affects non-tumour cells." (PMID 36497175, 2022). "The expression of three hub genes, COL7A1, MSLN, and CHRDL1, was significantly correlated with tumor-infiltrating monocytes." (PMID 35993054, 2022). "CDH3 was highly expressed in tumor samples, whereas high expression of CTGF, CYR61, OGN, FGF13, and CHRDL1 was associated with better prognosis and appeared to be a protective factor." (PMID 33816258, 2021). "In vivo experiments have confirmed that CHRDL1 is a tumor suppressor gene that inhibits tumor growth and metastasis." (PMID 32337286, 2020). "Through analysis of TCGA database, we found CHRDL1 was significantly down-regulated in tumor tissues as compared with non-tumor tissues." (PMID 28423564, 2017). "Taken together, our data demonstrates that CHRDL1 acts as a tumor suppressor that is regulated by promoter DNA methylation." (PMID 28423564, 2017). "Our study is the first to clarify the methylation-mediated suppression of CHRDL1 expression and its contribution to the enhanced migratory potential of tumor cells." (PMID 28423564, 2017). "After six weeks of injection, the tumor nodes in the CHRDL1 KD group were significantly larger than those in the NC group." (PMID 28423564, 2017). "In vitro, CHRDL1 knockdown promoted tumor cell proliferation and migration through BMPR II by activating Akt, Erk and β-catenin." (PMID 28423564, 2017). "Strikingly, the Chordin-like 1 levels were considerably higher in non-tumor forming clones (CMT-U353 clone 3) and in a clone that formed tumors without bone (CMT-U353 B clone 6) than in bone-forming clones (CMT-U353 B clones 2 and 7)." (PMID 19771160, 2009). "CHRDL1 inhibits cell proliferation and migration, and its expression is reduced in tumor tissues." (PMID 39462350, 2024). "The tumor-suppressive functions of CHRDL1 and FAM107A were validated in two LUSC cell lines." (PMID 38188687, 2023). "The CHRDL1 expression was evidently downregulated in THCA tumor tissues (P < .001)." (PMID 36749222, 2023). "Besides, it was obvious that mRNA expression of CHRDL1 was significantly downregulated in most tumor tissues of paired samples based on the data from TCGA database (P < .001)." (PMID 36749222, 2023). "Mechanistically it was shown that the upregulation of CHRDL1 expression results in the counteraction of the tumour-suppressive effects of BMP4 and that the depletion of CHRDL1 significantly reduces cell proliferation and sphere formation as well as tumour growth in a xenograft model." (PMID 36497175, 2022). "Three hub genes, COL7A1, MSLN, and CHRDL1, were identified from 513 robust DEGs using a series of bioinformatics methods, which were significantly correlated with tumor-infiltrating monocytes as well as effective indicators of prognostic outcomes for LUSC patients." (PMID 35993054, 2022). "Our study demonstrated that CHRDL1 was negatively correlated with tumor-infiltrating monocytes as well as may be a novel prognostic biomarker and therapy target in LUSC." (PMID 35993054, 2022). "The GEPIA database was searched to analyze CHRDL1 expression between the tumor and normal groups." (PMID 35494000, 2022). "Furthermore, multivariate analysis suggested that CHRDL1 was independently correlative with OS, with a HR of 0.563(P=0.016), along with primary therapy outcome (HR=2.022, P=0.002) and tumor status (HR=5.956, P<0.001)." (PMID 35021154, 2022). "ADAMTS18 and CHRDL1 are putative tumor suppressor genes and epigenetic silencing of these genes diagnosed with various cancer types, but inactivation of these genes might be linked with progression of pituitary prolactinoma." (PMID 33709028, 2021).
tumor (continued). "Finally, in vivo experiments confirmed that CHRDL1 acted as a tumor suppressor gene in suppressing tumor growth and metastasis." (PMID 28423564, 2017). "Furthermore, we observed that CHRDL1 protein expression was closely correlated with tumor progression, including local invasion, lymph node metastasis and TNM stage." (PMID 28423564, 2017). "Moreover, CHRDL1 was proven to inhibit tumor metastasis in vivo." (PMID 35494000, 2022). "Among them, the expression of CHRDL1, P2RX1, GCSAML, and APOC4-APOC2 in the tumor region was significantly lower than that in the normal region." (PMID 40860241, 2025). "CHRDL1 exerts a complex influence on cancer development and progression, particularly in LUAD, by impacting tumor progression, immune regulation, chemosensitivity, and EMT regulation." (PMID 40230414, 2025). "In TCGA-LUAD cohort, the expressions of CHRDL1, P2RX1, GCSAML and APOC4-APOC2 in tumor tissues were significantly lower than those in normal tissues, indicating the tumor-suppressing role of these genes in LUAD." (PMID 40860241, 2025). "Among the candidate genes, we also verified that the forced overexpression of CHRDL1 and FAM107A showed tumor suppressive activity in LUSC cell lines." (PMID 38188687, 2023). "CDH3 was found to be highly expressed, while CTGF, CYR61, CHRDL1, OGN and FGF13 had significantly lower expression in tumor tissues compared with peri-tumor tissues." (PMID 33816258, 2021). "Comparing with peri-tumor controls, the expression of CTGF, CYR61, CHRDL1, OGN and FGF13 were significantly decreased, whereas CDH3 significantly increased in PTC tissues which were consistent with the bioinformatics results obtained by TCGA dataset." (PMID 33816258, 2021). "In vitro, CHRDL1 knockdown promotes tumor cell proliferation by activating AKT, ERK and β-catenin and boosts tumor cell migration through BMPR II." (PMID 32337286, 2020). "CHRDL1, by modulating the activity of bone morphogenetic proteins (BMPs), plays an important role in regulating TGF-β signaling and extracellular matrix remodeling, both of which are essential in the tumor microenvironment (TME)." (PMID 40230414, 2025). "Besides, high levels of CHRDL1 inhibited BMP4-induced Smad1/5/8 phosphorylation, thereby suppressing tumor growth." (PMID 40837015, 2025). "Given that the effects of CHRDL1 primarily targeted tumor migration and adhesion rather than proliferation, we established a xenograft model to evaluate its impact on in vivo metastasis." (PMID 40837015, 2025). "Furthermore, CHRDL1 expression levels decreased with advancing tumor stages of LUAD, aligning with prior bioinformatics analyses and substantiating the correlation between CHRDL1 expression and clinical pathology." (PMID 40230414, 2025). "Subsequent analysis within the TCGA-LUAD cohort confirmed a negative correlation between CHRDL1 expression levels and the progression of T, N, and M tumor stages." (PMID 40230414, 2025). "Together, these data strongly suggest that CHRDL1 and FAM107A may act as tumor suppressors in LUSC cells." (PMID 38188687, 2023). "The results indicated that the upregulated hub genes COL7A1 and JUP were negatively correlated with tumor-infiltrating monocytes, while the downregulated hub genes MSLN and CHRDL1 were positively correlated with tumor-infiltrating monocytes, with a p value < 0.05." (PMID 35993054, 2022). "Another integrated mRNA–lncRNA signature was developed based on the mRNA species for FCGR1A, RSAD2, CHRDL1, and the lncRNA species for HIF1A-AS2 and AK124454, which may be applied to predict tumor recurrence and the benefit of taxane chemotherapy in TNBC." (PMID 33194705, 2020). "Moreover, CHRDL1 antagonizes the function of BMP4 by binding to it and preventing its interaction with receptors, resulting in tumor-suppressing effects in patients with BC." (PMID 32775417, 2020).
tumor (continued). "Corroborating previous bioinformatics analysis, which showed a negative correlation between CHRDL1 expression and tumor staging, we hypothesized that CHRDL1 might influence the invasive and metastatic capabilities of LUAD cells." (PMID 40230414, 2025). "However, there was little staining of CHRDL1 in either the tumor stroma in OSCC or subepithelial tissues in the adjacent normal tissues." (PMID 35494000, 2022). "This maybe indicate that CHRDL1 is mainly involved in the regulation of tumor growth rather than tumor migration and invasion." (PMID 35021154, 2022). "However, in this study, the effect of HIF1A-AS2 and CHRDL1 in determining the growth pattern of the tumor based on US was not studied in animals." (PMID 33542899, 2020).
cancer (20 papers, 2010 to 2025). A tumor composed of atypical neoplastic, often pleomorphic cells that invade other tissues. "The results of univariate Cox regression analysis demonstrated that OS of 12 types of cancers was substantially associated with expression level of CHRDL1 (p < 0.05)." (PMID 40230414, 2025). "In certain cancers, elevated CHRDL1 expression was linked to poorer survival outcomes, whereas in LUAD, it was associated with improved survival." (PMID 40230414, 2025). "Accumulating evidence suggests that dysregulation of Chordin-like 1 (CHRDL1) is associated with malignant biological behaviors in multiple cancers." (PMID 35494000, 2022). "In general, in pan-cancer, most frequent mutation type of CHRDL1 was missense mutation." (PMID 40230414, 2025). "Therefore, the abnormal decrease of CHRDL1 may cause the excessive proliferation of cancer cells through activation of cell cycle checkpoint." (PMID 35021154, 2022). "Our study extensively explored the expression patterns and prognostic value of CHRDL1 in pan-cancer." (PMID 40230414, 2025). "This study aims to bridge this knowledge gap by conducting a pan-cancer analysis of CHRDL1 expression across multiple cancer types, with a particular focus on LUAD." (PMID 40230414, 2025). "In conclusion, this study, through comprehensive bioinformatics analysis and experimental validation, depicts the expression patterns of CHRDL1 in various cancers, particularly emphasizing its role in LUAD." (PMID 40230414, 2025). "The primary objective of this study is to conduct a pan-cancer analysis of CHRDL1 expression, to determine its correlation with patient survival rates, immune cell infiltration, and drug sensitivity." (PMID 40230414, 2025). "The implications of CHRDL1 expression in cancer progression remain poorly understood, particularly in terms of its influence on patient prognosis, immune infiltration, and therapeutic sensitivity." (PMID 40230414, 2025). "In the immune cycle activity scores of LUAD, CHRDL1 is significantly positively correlated with Step2 cancer antigen presentation (cor = 0.472, p < 0.05) and Step4 CD4 T cell recruitment (cor = 0.435, p < 0.05)." (PMID 40230414, 2025). "In conclusion, we have identified CHRDL1 as a novel cancer suppressor gene in OSCC that targets the oncogenic MED29." (PMID 39462350, 2024). "The CHRDL1 expressions between kinds of cancers and normal tissues were determined by the analysis of TCGA and genotype-tissue expression data." (PMID 36749222, 2023). "We used the cBioPortal online platform to predict CHRDL1 co-expressed genes within the TCGA pan-cancer atlas." (PMID 36749222, 2023). "For example, we found that CHRDL1 also promoted the PI3K-Akt signal pathway which promoted the development of cancer." (PMID 36749222, 2023). "The roles of CHRDL1, a BMPS antagonist associated with various cancers, should be more deeply explored." (PMID 35494000, 2022). "All the findings about the expression of CHRDL1 were consistent with our results in pan-cancer, and this also proved the reliability and authenticity of our study." (PMID 35021154, 2022). "CHRDL1 is a secreted glycoprotein and a BMP antagonist associated with various cancers." (PMID 40837015, 2025). "The DSS of 12 types of cancers was also dramatically related to expression level of CHRDL1." (PMID 40230414, 2025). "CHRDL1 may be involved in signal pathway related to cancer development and immune response, which suggested it could be a potential biomarker." (PMID 36749222, 2023). "Thus, in this study, we collected CHRDL1 expression and survival data from The Cancer Genome Atlas (TCGA) database and further determine the role of CHRDL1 in the development of THCA through bioinformatics analysis." (PMID 36749222, 2023). "Pan-cancer analysis showed CHRDL1 was also low expressed in most types of tumors." (PMID 35021154, 2022). "This suggests that CHRDL1 may be able to protect our body against the invasion of cancer through innate immunity." (PMID 35021154, 2022).